MOV10 (Mov10 RNA helicase)
Description:
5'-3' RNA helicase. Involved in a number of cellular roles ranging from mRNA metabolism and translation, modulation of viral infectivity, inhibition of retrotransposition, or regulation of synaptic transmission. Plays an important role in innate antiviral immunity by promoting type I interferon production. Mechanistically, specifically uses IKKepsilon/IKBKE as the mediator kinase for IRF3 activation. Blocks HIV-1 virus replication at a post-entry step. Counteracts HIV-1 Vif-mediated degradation of APOBEC3G through its helicase activity by interfering with the ubiquitin-proteasome pathway. Also inhibits hepatitis B virus/HBV replication by interacting with HBV RNA and thereby inhibiting the early step of viral reverse transcription. Contributes to UPF1 mRNA target degradation by translocation along 3' UTRs. Required for microRNA (miRNA)-mediated gene silencing by the RNA-induced silencing complex (RISC). Required for both miRNA-mediated translational repression and miRNA-mediated cleavage of complementary mRNAs by RISC. In cooperation with FMR1, regulates miRNA-mediated translational repression by AGO2. Restricts retrotransposition of long interspersed element-1 (LINE-1) in cooperation with TUT4 and TUT7 counteracting the RNA chaperonne activity of L1RE1. Facilitates LINE-1 uridylation by TUT4 and TUT7. Required for embryonic viability and for normal central nervous system development and function. Plays two critical roles in early brain development: suppresses retroelements in the nucleus by directly inhibiting cDNA synthesis, while regulates cytoskeletal mRNAs to influence neurite outgrowth in the cytosol (By similarity). May function as a messenger ribonucleoprotein (mRNP) clearance factor. (Microbial infection) Required for RNA-directed transcription and replication of the human hepatitis delta virus (HDV). Interacts with small capped HDV RNAs derived from genomic hairpin structures that mark the initiation sites of RNA-dependent HDV RNA transcription.
Synonyms: gb110; MGC2948; fSAP113
Tractability: PROTAC: UniProt records ubiquitination sites on it; ubiquitination databases record sites on it; its protein half-life has been measured.
Gene: Protein-coding gene on chromosome 1 (112,673,141 to 112,702,383, forward strand). Ensembl gene ENSG00000155363.
Subcellular location: Cytoplasm, P-body; Cytoplasm, Cytoplasmic ribonucleoprotein granule; Cytoplasm, Stress granule; Nucleus; Cytoplasm
Subcellular location (Human Protein Atlas): Cytosol
Pathways (Reactome):
Signal Transduction: Ca2+ pathway; Competing endogenous RNAs (ceRNAs) regulate PTEN translation; Estrogen-dependent gene expression; MAPK6/MAPK4 signaling; MTOR signalling; NR1H3 & NR1H2 regulate gene expression linked to cholesterol transport and efflux; Pre-NOTCH Transcription and Translation; Regulation of PTEN mRNA translation; TGFBR3 expression
Gene expression (Transcription): RUNX1 regulates genes involved in megakaryocyte differentiation and platelet function; Regulation of NPAS4 mRNA translation; Regulation of RUNX1 Expression and Activity; Transcriptional Regulation by VENTX
Cell-Cell communication: Regulation of CDH1 mRNA translation by microRNAs; Regulation of CDH11 mRNA translation by microRNAs
Cellular responses to stimuli: Oncogene Induced Senescence; Oxidative Stress Induced Senescence
Developmental Biology: Regulation of MITF-M-dependent genes involved in apoptosis
Disease: Nuclear events stimulated by ALK signaling in cancer
Immune System: Regulation of PD-L1(CD274) translation
Gene Ontology:
Molecular function: 5'-3' RNA helicase activity; ATP hydrolysis activity; protein binding; RNA binding; helicase activity
Biological process: 3'-UTR-mediated mRNA destabilization; defense response to virus; miRNA-mediated gene silencing by mRNA destabilization; miRNA-mediated post-transcriptional gene silencing; positive regulation of mRNA catabolic process; transposable element silencing; transposable element silencing by mRNA destabilization; regulation of neuron projection arborization; spermatogenesis; T cell activation
Cellular component: cytoplasmic ribonucleoprotein granule; extracellular region; P-body; cytoplasm; cytosol; nucleus; P granule; cytoplasmic stress granule
Genetic constraint (gnomAD): Loss-of-function variants: 36 observed, 109.38 expected, observed/expected ratio (o/e) 0.33, 90% interval 0.25 to 0.44. The upper end of that interval is the gene's LOEUF score, 0.44, which puts it in group 1 of 6, group 1 being the genes least tolerant of losing a copy. Missense variants: 951 observed, 1,350 expected, observed/expected ratio (o/e) 0.7, 90% interval 0.67 to 0.74. Synonymous variants: 490 observed, 545.09 expected, observed/expected ratio (o/e) 0.9, 90% interval 0.83 to 0.97.
Homologues: Orthologues: chimpanzee MOV10 (99% identical), macaque MOV10 (99% identical), dog MOV10 (94% identical), rat Mov10 (92% identical), mouse Mov10 (91% identical), pig MOV10 (90% identical), rabbit MOV10 (90% identical), guinea pig MOV10 (88% identical), tropical clawed frog mov10 (46% identical), tropical clawed frog XB5951253 (45% identical), zebrafish mov10a (43% identical), zebrafish mov10b.2 (43% identical), and 4 more. Paralogues in human: MOV10L1 (30% identical), HELZ (20% identical), HELZ2 (19% identical), ZNFX1 (16% identical), SETX (16% identical), AQR (15% identical), DNA2 (14% identical), UPF1 (14% identical), IGHMBP2 (14% identical), CT55 (3% identical).
Diseases named in the same sentence as MOV10 in open-access papers:
MOV10 is named in the same sentence as 36 diseases in open-access papers, as found by Europe PMC text mining. Sharing a sentence is not in itself a finding about the gene and the disease. The quoted sentences say what the papers report.
viral infection (9 papers, 2020 to 2024). "Depletion of MOV10 promoted viral infection of SFTSV, HRTV and GTV, suggesting an antiviral role of MOV10 against these viruses." (PMID 38711929, 2024). "MOV10 was also found to play a role in innate immune response against viral infection via modulation of IFN signaling." (PMID 38711929, 2024). "We also demonstrated mov10 genes were upregulated upon virus challenge, highlighting they had redundant conserved roles in virus infection." (PMID 35886872, 2022). "We also demonstrated MOV10 genes are upregulated by virus challenge, highlighting they have redundant conserved roles in virus infection." (PMID 35886872, 2022). "Thus, the multi-protein complex, consisting of A3B, PABPC1, DDX3, and MOV10 is pre-formed in cells and relocates to SGs after viral infection." (PMID 36781883, 2023). "One critical role of MOV10 is antiviral activity in human and mouse, the infected cells upregulate the expression of MOV10 in response to virus and MOV10 could inhibit viral infection by several different strategies." (PMID 35886872, 2022). "In addition, MOV10 is an interferon-stimulated gene (ISG), and MOV10 protein is involved in IFN induction after viral infection." (PMID 34517762, 2021). "Because of the strong interaction of MOV10 with N and the essential role of N in virus infection as the main RNP component, we considered that by targeting N, MOV10 may interfere with RNP and hence virus replication." (PMID 33284835, 2020). "Since MOV10 showed remarkable anti-bunyavirus activity in cultured cells, we asked whether MOV10 affects the virus infection and pathogenicity in vivo." (PMID 33284835, 2020). "In this work we also draw connections between ZCCHC3 and the RNA helicase MOV10 and zinc-finger protein ZAP, host proteins known to restrict viral infection in mammals and previously shown by ourselves and others to potently inhibit human retrotransposition." (PMID 37405998, 2023). "We identified EP300, MOV10, RELA, and TRIM25 as top candidates, and more than 60 additional proteins involved in the epigenetic response during viral infection that has therapeutic potential." (PMID 34031419, 2021). "Indeed, we discovered an association between ZCCHC3 and the better-characterized interferon-stimulated gene products MOV10 and ZAP, host proteins known to restrict viral infection in mammals and previously shown by ourselves and others to potently inhibit cell culture retrotransposition." (PMID 37405998, 2023).
glioma (6 papers, 2019 to 2025). A benign or malignant brain and spinal cord tumor that arises from glial cells (astrocytes, oligodendrocytes, ependymal cells). "This molecular axis of MOV10/circ-DICER1/miR-103a-3p/miR-382-5p/ZIC4 gives novel insights into glioma angiogenesis, providing prospective targets for anti-angiogenesis strategy." (PMID 31937318, 2020). "MOV10 is regarded as an important regulator of the nervous system, which promotes angiogenesis of glioma cells by regulating cell activity, migration, and tube formation." (PMID 33001583, 2020). "MOV10 / circ-DICER1 / miR-103a-3p (miR-382-5p) / ZIC4 pathway plays a vital role in regulating the angiogenesis of glioma." (PMID 30621721, 2019). "Consequently, MOV10/circ-DICER1/miR -103a-3p (miR-382-5p)/ZIC4 pathway plays a vital role in regulating the angiogenesis of glioma." (PMID 30621721, 2019). "MOV10 can bind to circ-DICER1 and modulate the cell viability, migration, and angiogenesis in glioma." (PMID 40061896, 2025). "RBP MOV10 that bound to circ-DICER1 induced the proliferation, migration as well as tube formation in glioma cells via activation of PI3K/Akt pathway." (PMID 33634155, 2021). "Recent studies reveal that glioma-exposed endothelial cells (GECs) exhibit high expression of circRNA DICER1 (circ-DICER1) and its RBP MOV10." (PMID 31937318, 2020). "Other studies confirmed that RNA-binding proteins MOV10 and FUS also bound to circRNAs and positively regulated their expressions to promote the angiogenesis of gliomas, which is consistent with our results." (PMID 31296839, 2019). "The purpose of this study is to elucidate the potential roles and molecular mechanisms of MOV10 and circ-DICER1 in regulating the angiogenesis of glioma-exposed endothelial cells (GECs)." (PMID 30621721, 2019). "In addition, the binding site of MOV10 and circ-DICER1 was confirmed with the help of CircInteracome database, and the result of RIP demonstrated MOV10 promoted the angiogenensis of glioma by targeting circ-DICER1." (PMID 30621721, 2019). "At present, the role of MOV10 has not been reported in the angiogenesis of glioma." (PMID 30621721, 2019).
neuroblastoma (4 papers, 2017 to 2022). Neuroblastoma (NB) is the most common solid, extracranial childhood tumor. "It was previously shown that loss of MOV10 and FMRP results in shorter neurites in a murine neuroblastoma cell line (Neuro2A) compared to WT." (PMID 34847178, 2021). "MOV10 and FMRP modulate expression of DICER1 mRNA through its 3’untranslated region (UTR) and introduction of a DICER1 transgene restores normal neurite outgrowth in the Mov10 KO neuroblastoma Neuro2A cell line and branching in MOV10 heterozygote neurons." (PMID 34847178, 2021). "To determine if Mov10 functions in neurite outgrowth, we used Clustered regularly interspaced short palindromic repeats (CRISPR)-Cas9 to knock out Mov10 in cells of Neuro2a (N2a), a murine neuroblastoma that has long branching processes when grown on a substrate." (PMID 28662698, 2017).
Anxiety (3 papers, 2017 to 2022). Intense feelings of nervousness, tension, or panic often arise in response to interpersonal stresses. "They found that Mov10 level is elevated in the postnatal mouse brain and that Mov10 KO has an embryonic lethal phenotype, while heterozygous Mov10+/− mice have disrupted dendritic arborization, increased anxiety and hyperactivity." (PMID 35628657, 2022). "Unlike FMRP, the Mov10 knockout (KO) is embryonic lethal; however the Mov10 heterozygous (Het) mouse has increased anxiety and hyperactivity, which are features shared with Fragile X syndrome and suggest impaired neuronal function." (PMID 34847178, 2021). "Reduced Mov10 in murine brain resulted in anxiety and increased activity in a novel environment, supporting its important role in the development of normal brain circuitry." (PMID 28662698, 2017). "Accordingly, the Mov10 heterozygote mice show increased activity in a novel environment and higher anxiety, suggesting that Mov10 is required for normal brain function." (PMID 28662698, 2017). "The increased activity in a novel environment and increased anxiety seen in the Mov10 heterozygotes suggests that an element of the neuronal circuitry is perturbed in these mice." (PMID 28662698, 2017). "The Mov10 heterozygotes also spent significantly less time in the open arms in an elevated plus maze test, suggesting an anxiety phenotype." (PMID 28662698, 2017). "Finally, reduced Mov10 in the murine brain results in anxiety and increased activity in a novel environment." (PMID 28662698, 2017). "To determine whether reduced Mov10 levels affected neuronal function, we tested the Mov10 heterozygotes in behavioral tests and found that the Mov10 heterozygote showed a significant increase in activity in an open field compared to WT littermates, suggesting anxiety and/or hyperactive behavior." (PMID 28662698, 2017).
Alzheimer disease (2 papers, 2017 to 2022). A progressive, neurodegenerative disease characterized by loss of function and death of nerve cells in several areas of the brain leading to loss of cognitive function such as memory and language. "This is a completely new and critically important function for Mov10 in neuronal development and establishes a precedent for Mov10 being an important candidate in neurological disorders that have underlying cytoarchitectural causes like autism and Alzheimer’s disease." (PMID 28662698, 2017).
bunyavirus infection (2 papers, 2020 to 2021). "Collectively, these data manifest that MOV10 can be specifically and sustainably upregulated by the bunyavirus infections, while its induction by type I IFN seems relatively weak, compared with the tested classical ISGs." (PMID 33284835, 2020). "Given the strong interaction of MOV10 with N and cellular upregulation of MOV10 upon bunyavirus infection, we considered that MOV10 might modulate the bunyavirus replication." (PMID 33284835, 2020). "It will be interesting to further delineate the mechanism for the specific upregulation of MOV10 in response to SFTSV and the related bunyavirus infections." (PMID 33284835, 2020). "This was in contrast to the absence of a MOV10 helicase activity requirement for antiviral activity during HIV-1, influenza virus, HCV, or bunyavirus infections, strongly suggesting that MOV10 can exert its antiviral function by different mechanisms in different RNA viruses." (PMID 34517762, 2021).
Hypertension (2 papers, 2021). The presence of chronic increased pressure in the systemic arterial system. "The rs2932538, located in noncoding region of MOV10, was proved to have association with hypertension in Europeans and Chinese." (PMID 33269545, 2021). "Furthermore, a case‐control study conducted recently in the Chinese Han population proved that polymorphism of rs2932538 in MOV10 gene have relationship with the increased risk of hypertension." (PMID 33269545, 2021). "A previous Genome‐wide association study (GWAS) of blood pressure using a multistage design in European populations by the International Consortium for Blood Pressure Genome Wide Association Studies have identified the MOV10 rs2932538 as a locus significantly associated with hypertension." (PMID 33269545, 2021). "Of the genes overexpressed in patients before or after HCT, WNK1 is associated with a monogenic type of hypertension, while BAT2D1, MOV10, PIK3CG are genetic variants associated with BP5,25." (PMID 33927307, 2021). "Another GWAS of blood pressure and hypertension in Chinese population replicated the loci was associated with blood pressure at genome‐wide significance, SNPs in CASZ1, FGF5, CYP17A1, and MOV10 were included." (PMID 33269545, 2021).
influenza (2 papers, 2023 to 2025). An acute viral infection of the respiratory tract, occurring in isolated cases, in epidemics, or in pandemics; it is caused by serologically different strains of viruses (influenzaviruses) designated A, B, and C, has a 3-day incubation period, and usually lasts for 3 to 10 days. "MOV10 is an interferon-inducible 110-kDa RNA helicase with an important role in the defense against viruses, including influenza, hepatitis B, and human immunodeficiency virus." (PMID 39606792, 2023). "A similar pattern was observed for the MOV10 and ZC3HAV1 genes, host factors that restrict influenza replication; their induction was attenuated by milk in A549 cells." (PMID 41157297, 2025).
lung adenocarcinoma (2 papers, 2020 to 2021). A carcinoma that arises from the lung and is characterized by the presence of malignant glandular epithelial cells. "MOV10, encoding Mov10 RISC complex RNA helicase, was reported to be highly expressed with POLR2A, MAPK3, and XAB2 in 95% of 54 lung adenocarcinoma (LUAD) cases with poor prognosis." (PMID 34616428, 2021). "High expression of POLR2A, MAPK3, MOV10, and XAB2 predicted poor prognosis in lung adenocarcinoma, as verified by the K‐M plotter database." (PMID 33001583, 2020). "The K‐M plotter database indicated that high expression of POLR2A, MAPK3, MOV10, and XAB2 predicted poor prognosis in lung adenocarcinoma." (PMID 33001583, 2020).
malignant melanoma (2 papers, 2015 to 2019). "In melanoma, inhibition of MOV10 increases the synthesis and secretion of Wnt 5a to further affect the metastasis of melanoma cells." (PMID 30621721, 2019). "Identifying the molecular changes that decrease Mov10 expression in melanoma warrants further study." (PMID 26029828, 2015). "We show Mov10 protein levels are reduced in melanoma tumor samples stained by immunohistochemistry when compared with benign nevi." (PMID 26029828, 2015). "Inhibition of Mov10 increases secreted Wnt5a levels in melanoma cells by increasing Wnt5a synthesis and acylation." (PMID 26029828, 2015). "We observed high-Mov10-expressing cells are most commonly benign tumors with low FASN expression, whereas low-Mov10-expressing tumors with high FASN expression were more often malignant melanoma." (PMID 26029828, 2015). "The melanoma samples that were derived from secondary tumors expressed higher levels of Mov10 than the primary tumor samples, but were lower than the benign tumors." (PMID 26029828, 2015). "Next, Mov10 expression was inhibited by shRNA in the moderate Wnt5a secreting melanoma cell line UACC903." (PMID 26029828, 2015). "Our studies reveal a previously unreported role for Mov10 in regulating the Wnt5a signaling pathway during melanoma progression." (PMID 26029828, 2015). "Reduction of Mov10 expression by short hairpin RNA (shRNA) increases the level of lipid modified and secreted Wnt5a in melanoma cell lines." (PMID 26029828, 2015). "The Mov10 protein levels in benign nevi were found to be higher than levels observed in the malignant melanoma." (PMID 26029828, 2015). "Mov10-FLAG was ectopically expressed in the high Wnt5a secreting melanoma cell lines FS5 and M93-047." (PMID 26029828, 2015). "Melanoma tumors exhibit reduced expression of Mov10 compared with benign nevi and Mov10 levels inversely correlate with FASN levels in primary tumors." (PMID 26029828, 2015). "We asked whether the expression of FASN or SCD also correlated with Mov10 expression in human melanoma tumors." (PMID 26029828, 2015). "Our studies indicate that Mov10 shRNA increases expression of FASN and SCD in cultured melanoma cell lines promoting Wnt5a secretion." (PMID 26029828, 2015). "When the secondary tumors are excluded, there is a negative correlation between Mov10 and FASN expression levels in melanoma tumors (r= −0.27; P<0.01; N=141)." (PMID 26029828, 2015). "Quantification of Mov10 and FASN levels reveal a negative correlation between Mov10 and FASN protein expression in primary melanoma and benign tumors." (PMID 26029828, 2015).